SCAP (SREBF chaperone)
Description:
Escort protein required for cholesterol as well as lipid homeostasis (By similarity). Regulates export of the SCAP-SREBP complex from the endoplasmic reticulum to the Golgi upon low cholesterol, thereby regulating the processing of sterol regulatory element-binding proteins (SREBPs) SREBF1/SREBP1 and SREBF2/SREBP2. At high sterol concentrations, formation of a ternary complex with INSIG (INSIG1 or INSIG2) leads to mask the ER export signal in SCAP, promoting retention of the complex in the endoplasmic reticulum (By similarity). Binds cholesterol via its SSD domain (By similarity).
Synonyms: KIAA0199
Tractability: Small molecule: a structure with a bound ligand is known. Antibody: UniProt predicts a signal peptide or a membrane-spanning region. PROTAC: UniProt records ubiquitination sites on it; ubiquitination databases record sites on it; its protein half-life has been measured.
Gene: Protein-coding gene on chromosome 3 (47,413,681 to 47,477,126, reverse strand). Ensembl gene ENSG00000114650.
Subcellular location: Endoplasmic reticulum membrane; Golgi apparatus membrane; Cytoplasmic vesicle, COPII-coated vesicle membrane
Pathways (Reactome):
Disease: Maturation of DENV proteins
Metabolism: Regulation of cholesterol biosynthesis by SREBP (SREBF)
Gene Ontology:
Molecular function: protein binding; sterol binding; protein-containing complex binding
Biological process: cholesterol metabolic process; positive regulation of cholesterol biosynthetic process; regulation of transcription by RNA polymerase II; SREBP signaling pathway; COPII-coated vesicle cargo loading; negative regulation of cholesterol biosynthetic process; regulation of cholesterol biosynthetic process; response to vitamin B3
Cellular component: endoplasmic reticulum membrane; Golgi membrane; SREBP-SCAP complex; endoplasmic reticulum; Golgi apparatus; membrane; SREBP-SCAP-Insig complex; ER to Golgi transport vesicle membrane; protein-containing complex
Genetic constraint (gnomAD): Loss-of-function variants: 65 observed, 119.45 expected, observed/expected ratio (o/e) 0.54, 90% interval 0.44 to 0.67. The upper end of that interval is the gene's LOEUF score, 0.67, which puts it in group 2 of 6, group 1 being the genes least tolerant of losing a copy. Missense variants: 1,398 observed, 1,712.9 expected, observed/expected ratio (o/e) 0.82, 90% interval 0.78 to 0.85. Synonymous variants: 740 observed, 724.57 expected, observed/expected ratio (o/e) 1.02, 90% interval 0.96 to 1.09.
Homologues: Orthologues: chimpanzee SCAP (99% identical), rabbit SCAP (94% identical), dog SCAP (93% identical), macaque SCAP (93% identical), pig SCAP (93% identical), rat Scap (92% identical), mouse Scap (92% identical), guinea pig SCAP (86% identical), tropical clawed frog scap (72% identical), zebrafish scap (69% identical), Drosophila melanogaster SCAP (32% identical). Paralogues in human: DISP1 (15% identical), DISP2 (14% identical), PTCH1 (10% identical), NPC1 (10% identical), NPC1L1 (10% identical), PTCH2 (10% identical), DISP3 (7% identical), PTCHD1 (7% identical), PTCHD3 (7% identical), PTCHD4 (6% identical).
Diseases named in the same sentence as SCAP in open-access papers:
SCAP is named in the same sentence as 92 diseases in open-access papers, as found by Europe PMC text mining. Sharing a sentence is not in itself a finding about the gene and the disease. The quoted sentences say what the papers report.
Obesity (15 papers, 2009 to 2025). Accumulation of substantial excess body fat. "At the same time, the single association analyses of the same study only found a significant association between SCAP rs12487736 and obesity." (PMID 35295960, 2022). "Accordingly, dysregulation of the SCAP-SREBP pathway has been reported to be closely associated with an increased risk of obesity, hypercholesterolemia, and cardiovascular disease." (PMID 34094640, 2021). "Recently, it was found that two polymorphisms (rs12487736 and rs12490383) in SCAP were related to obesity in Chinese children." (PMID 28542467, 2017). "The SCAP rs12487736 and rs12490383 were nominally significantly associated with obesity after adjustment for sex, age, age square, and study population (P = 0.039 and 0.026, resp)." (PMID 25028659, 2014). "Proinflammatory macrophage infiltration in adipose tissue induced by high-fat and high sucrose diet is also increased by SCAP deletion, highlighting the role SCAP in determining macrophage phenotype and associated cytokines secretion in obesity and other metabolic diseases." (PMID 39198360, 2025). "Together with SREBP-cleavage activating proteins (SCAP), they are crucial for maintaining cellular lipid homeostasis; hence their aberrant activation is known to cause fatty liver disease, insulin resistance, obesity, and cancer development." (PMID 36290086, 2022). "Additionally, we found that two SCAP SNPs (rs12487736 and rs12490383) had association with obesity (nominal P value <0.05)." (PMID 25028659, 2014). "However, the underlying mechanism how SCAP affect both obesity and BP remains to be explored." (PMID 28542467, 2017). "Here, we report that in fatty liver caused by diet-induced obesity (DIO), hepatocyte SREBP cleavage–activating protein (SCAP) was required for Reverb-hDKO–induced diurnal rhythmic remodeling and epigenomic reprogramming in liver macrophages (LMs)." (PMID 37066875, 2023). "SCAP-mediated hyperlipidemia and hypertriglyceridemia are directly related to metabolic diseases such as arteriosclerosis, obesity, and type II diabetes." (PMID 32385422, 2020). "Previous studies demonstrated a role of variations in sterol regulatory element binding protein (SREBP) cleavage-activating protein (SCAP) in obesity and blood lipids." (PMID 28542467, 2017). "There were a few studies that focused on the relationship between the INSIG1, SCAP genes and obesity or plasma lipids." (PMID 25028659, 2014). "We identified a 3-locus interaction on obesity in GMDR analyses (P = 0.001), involving 3 genetic variants of INSIG2, SCAP, and SREBP2." (PMID 25028659, 2014). "Briefly, the SCAP pathway plays a crucial role in feedback regulation of lipid metabolism and may be involved in the development of obesity." (PMID 32385422, 2020). "SCAP, part of the INSIG-SCAP-SREBP pathway, is involved in obesity risk in Chinese children." (PMID 26083354, 2015). "With its biological function and results of genetic epidemiology researches, we could seriously consider the role of SCAP in obesity development." (PMID 25028659, 2014). "We found a 3-locus model involving 3 genes of INSIG-SCAP-SREBP pathway (INSIG2 rs9308762, SCAP rs12487736, and SREBP2 rs1883205) had significant gene-gene interaction on obesity (permutated P = 0.001)." (PMID 25028659, 2014). "In our study, the results of GMDR revealed that INSIG2 rs9308762, SCAP rs12487736, and SREBP2 rs1883205 of INSIG-SCAP-SREBP pathway have gene-gene interaction on obesity." (PMID 25028659, 2014). "Also, unknown epistatic interaction of the rs7566605 with one or other (rare) polymorphisms could lead to association with the more extreme obesity phenotype, with the INSIG2 gene being part of a complex that functions as a biological entity (SREBP, SCAP, INSIG2)." (PMID 19851442, 2009).
Obesity (continued). "In addition, in diet-induced obese mice, dietary xanthohumol reduced SCAP/SREBP target gene expression in the liver, thereby reducing the mature form of liver SREBP-1, which inhibited the development of obesity and hepatic steatosis." (PMID 32385422, 2020). "However, when we conducted a GMDR analysis, we found the significant interaction of the three genes (INSIG2 rs9308762, SCAP rs12487736, and SREBP2 rs1883205) on obesity." (PMID 25028659, 2014).
Hepatic steatosis (12 papers, 2016 to 2026). Steatosis is a term used to denote lipid accumulation within hepatocytes. "Previous studies have shown that suppression of SREBP activation in SCAP conditional knockout mice reduced the accumulation of intracellular triglycerides, which eventually causes the development of metabolic diseases such as atherosclerosis, diabetes, hepatic steatosis, and insulin resistance." (PMID 32385422, 2020). "For instance, liver-specific deletion of SCAP reduces hepatic steatosis but exacerbates liver injury, fibrosis, and carcinogenesis due to impaired lipid homeostasis and increased inflammation." (PMID 41522335, 2026). "In line, previous studies have shown that SCAP inhibition can resolve hepatic steatosis in animal models and intensive research is going on to understand the effects of SCAP in the pathogenesis of human disease." (PMID 38256181, 2024). "Recently, multiple studies have been focusing on targeting SCAP in animal models of insulin resistance, with the potential to translate these findings into clinical trials aimed at reducing hepatic steatosis." (PMID 38256181, 2024). "This review focuses on the versatile roles of SCAP/SREBP regulation in de novo lipogenesis and the structure and molecular features of SCAP/SREBP in the progression of hepatic steatosis." (PMID 38256181, 2024). "Loss of hepatocytic REV-ERBs also leads to disruption of LM rhythms, in part by SCAP/SREBP-independent regulation of PDGF, which regulates LM genes involved in vitamin D signaling pathways implicated in fatty liver and NASH." (PMID 37066875, 2023). "Histologically, PTENΔL mice showed mild hepatic steatosis at this age, while hepatic steatosis was almost abolished by additional SCAP deletion, as confirmed by oil red O staining." (PMID 35380992, 2022). "The hepatic steatosis evident in PTENΔL mice was reduced with the combined knockout of SCAP, consistent with the authors’ expectation." (PMID 35642642, 2022). "The results confirmed that the SREBP pathway is required for hepatic steatosis in PTENΔL mice; however, unexpectedly, SCAP/SREBP pathway inhibition markedly exacerbated liver injury, fibrosis, and carcinogenesis in PTENΔL mice." (PMID 35380992, 2022). "Unexpectedly, SREBP inhibition via deletion of the SREBP cleavage–activating protein (SCAP) in the liver exacerbated liver injury, fibrosis, and carcinogenesis despite markedly reduced hepatic steatosis." (PMID 35380992, 2022). "Genetic studies have shown that blocking SCAP in mice can reduce the development of diabetes, fatty liver disease and atherosclerosis." (PMID 32385422, 2020). "SCAP is a key regulator of lipid metabolism and a potential therapeutic target for treatment of dyslipidemia and fatty liver disease." (PMID 27707816, 2016). "Targeting SCAP could be more effective in alleviating hepatic steatosis because SCAP is a central regulator necessary for activating all three isoforms of SREBP." (PMID 38256181, 2024). "It is thus crucial to gain a deeper understanding of SCAP/SREBP regulation in MASLD, which may open avenues for novel therapeutic drug designs targeting the SCAP/SREBP axis for treating fatty liver and hypertriglyceridemia." (PMID 38256181, 2024). "This makes SCAP a key therapeutic target for resolving hepatic steatosis." (PMID 38256181, 2024). "This review provides comprehensive information on the association of SCAP/SREBP and de novo lipogenesis, its relation to hepatic steatosis, molecular features of SCAP/SREBP activity, and current studies and developments in targeting the SCAP/SREBP in the pharmacotherapy of hepatic diseases." (PMID 38256181, 2024). "In addition, it was shown that the liver-specific deletion of SCAP resulted in a 90% reduction of fatty acid synthesis rates and prevented hepatic steatosis in ob/ob mice models." (PMID 38256181, 2024).
Hepatic steatosis (continued). "Notably, liver deletion of SCAP also prevents fatty liver in diabetic, high-carbohydrate diet, and high-fat diet rodent models of NAFLD, demonstrating that the SREBP pathway is a therapeutic target for the treatment of NAFLD." (PMID 35642642, 2022). "Based on these observations from preclinical models, targeting SCAP may be of therapeutic benefit for treatment of dyslipidemia and fatty liver disease." (PMID 27707816, 2016). "LMs are critical in the progression from fatty liver to NASH, and, indeed, SCAP-dependent changes in hepatocytic lipid metabolism play a crucial role in producing gained rhythms of genes related to inflammation in KCs." (PMID 37066875, 2023). "This opens up potential targeting of SCAP in the liver for the treatment of dyslipidemia and potentially other metabolic diseases that are driven by increased SREBP activation such as fatty liver disease." (PMID 27707816, 2016). "Given the importance of SCAP/SREBP in the regulation of lipid metabolism, and its indispensable role in the pathogenesis of fatty liver, unraveling the multiple specific molecules and inhibitors targeting the SCAP/SREBP axis has become the focus of translational research." (PMID 38256181, 2024). "Insulin increases the expression of SREBP-1c, it promotes the mobilization of the SREBP-cleavage activating protein (SCAP)/SREBP-1c complex to the Golgi apparatus, SREBP-1c cleavage, and the successive processes leading to hepatic lipogenesis and hepatic steatosis." (PMID 34950104, 2021). "The involvement of GP73 in promoting SCAP stabilization, SCAP Golgi localization and the increased formation of SCAP-SREBP complex regardless of cholesterol content implicates its pathological roles in hepatic steatosis and HCC progression." (PMID 29097707, 2017). "In addition, the authors did not test the effect of heterozygous SCAP deletion, and it is possible that a partial reduction of SREBP activity will improve hepatic steatosis without causing ER stress." (PMID 35642642, 2022).
hepatocellular carcinoma (10 papers, 2019 to 2025). A malignant tumor that arises from hepatocytes. "In addition to SCAP-dependent SREBP activation during the progression of hepatocellular carcinoma (HCC), SCAP-independent regulation also plays a role." (PMID 38137501, 2023). "Xu and colleagues demonstrated that disrupting the interaction between INSIGs and SCAP (due to activation of the AKT/PCK1 axis in hepatocellular carcinoma cells) leads to activation of SREBPs and, consequently, lipogenesis that in turn increases cell proliferation." (PMID 38065937, 2023). "For instance, the deletion of the gene encoding SREBP cleavage‐activating protein (SCAP) in the liver leads to liver damage, which manifests as nonalcoholic steatohepatitis (NASH) and hepatocellular carcinoma (HCC)." (PMID 40145543, 2025). "Studies have shown that blocking the SREBP-1 pathway by inhibiting SREBP Cleavage Activating Protein (SCAP) can notably inhibit the progression of diethylnitrosamine-induced hepatocellular carcinoma (HCC)." (PMID 38082285, 2023). "In Hap1 and Hepa1-6 hepatoma cells, ablation of SPRING results in a reduction of SCAP and its mislocalization to the Golgi and decreases SREBPs signaling, independent of sterol status." (PMID 36969840, 2023). "SCAP is overexpressed in HCC tissues and hepatocellular carcinoma cell lines with sorafenib resistance, while SCAP inhibition could improve sorafenib sensitivity in sorafenib-resistant HCC cells." (PMID 35354475, 2022). "In non-alcoholic fatty liver disease-hepatocellular carcinoma (NAFLD-HCC), METTL3 enhances m6A methylation on the mRNA of sterol regulatory element-binding protein (SREBP) cleavage-activating protein (SCAP), promoting its translation and activating cholesterol biosynthesis." (PMID 39987091, 2025). "Our data thus indicate that elaidate, but not ruminant trans fatty acids, activate the SCAP–SREBP2 pathway in cultured hepatoma cells." (PMID 31327168, 2019). "EA also induced cholesterogenesis in Hepa1-6 hepatoma cells in vitro by activating the sterol regulatory element-binding protein (SREBP) cleavage-activating protein (SCAP), mostly by reducing intracellular free cholesterol and cholesterol-dependent SCAP repression." (PMID 35294666, 2022).
dyslipidemia (9 papers, 2015 to 2024). "The same group later reported an association of SREF1 and SCAP (SREBP cleavage-activation protein) SNPs with elevated risk of drug-induced metabolic syndrome in people with schizophrenia." (PMID 34575210, 2021). "In conclusion, siRNA-mediated inhibition of SCAP resulted in a significant reduction in circulating PCSK9 and LDL-C in rodent and primate models supporting SCAP as a novel target for the treatment of dyslipidemia." (PMID 27707816, 2016). "SREBP cleavage-activating protein (SCAP) is a key protein in the regulation of lipid metabolism and a potential target for treatment of dyslipidemia." (PMID 27707816, 2016). "In the lipid metabolism, studies reported that the four protein complexes including SREBP, SCAP, INSIG, and PGRMC1 in the endoplasmic reticulum may be the important regulators of dyslipidemia caused by AAPD12,61." (PMID 38760414, 2024). "Simultaneously, the in vivo transplantation results have also enlightened the prospect of SCAP-Ss as an effective therapeutic intervention for liverish patients with multiple manifestation of metabolic syndrome with poor disability and outcome including cirrhosis and fibrosis." (PMID 32399047, 2020). "Moreover, AGEs accumulation in liver promotes hepatosteatosis and dyslipidemia through the activation of SCAP (sterol-regulatory element binding protein cleavage-activating protein)—SREBP (sterol-regulatory element binding protein) lipogenetic pathway." (PMID 25750996, 2015). "g.) to improve dyslipidemia by down-regulating progesterone and ADIPOQ receptor 3 and inhibiting the SCAP/SREBP-1c signaling pathway." (PMID 37492087, 2023).